GSTM1 (glutathione S-transferase mu 1)
Description:
Conjugation of reduced glutathione to a wide number of exogenous and endogenous hydrophobic electrophiles. Involved in the formation of glutathione conjugates of both prostaglandin A2 (PGA2) and prostaglandin J2 (PGJ2). Participates in the formation of novel hepoxilin regioisomers.
Synonyms: GST1; MU; H-B; GSTM1-1; GSTM1a-1a; GSTM1b-1b; GTH4; GTM1; MU-1
Tractability: Small molecule: a structure with a bound ligand is known; it has a high-quality binding pocket. PROTAC: ubiquitination databases record sites on it; its protein half-life has been measured; a small molecule that binds it is known.
Target class: Enzyme; Transferase
Safety:
Unwanted effects reported when the protein is acted on. In parentheses: how it was acted on, where the effect was seen, and who reports it.
chance of achieving complete remission (source: ClinPGx)
cutaneous reactions (source: ClinPGx)
drug toxicities (source: ClinPGx)
hearing impairment (source: ClinPGx)
hepatotoxicity (source: ClinPGx)
neutropenia (source: ClinPGx)
poorer chance of achieving complete remission (source: ClinPGx)
Stevens-Johnson Syndrome/Toxic Epidermal Necrolysis (SJS/TEN) (source: ClinPGx)
Gene: Protein-coding gene on chromosome 1 (109,687,340 to 109,709,039, forward strand). Ensembl gene ENSG00000134184.
Subcellular location: Cytoplasm
Subcellular location (Human Protein Atlas): Cytosol; Cytokinetic bridge; Microtubules; Primary cilium; Primary cilium tip; Primary cilium transition zone
Pathways (Reactome):
Drug ADME: Azathioprine ADME; Paracetamol ADME
Metabolism: Glutathione conjugation
Gene Ontology:
Molecular function: enzyme binding; glutathione binding; glutathione transferase activity; protein homodimerization activity
Biological process: cellular detoxification of nitrogen compound; glutathione derivative biosynthetic process; glutathione metabolic process; hepoxilin biosynthetic process; nitrobenzene metabolic process; prostaglandin metabolic process; xenobiotic catabolic process
Cellular component: cytoplasm; cytosol
Homologues: Orthologues: chimpanzee GSTM1 (99% identical), mouse Gstm2 (84% identical), rat Gstm5l (81% identical), rat Gstm1 (79% identical), mouse Gstm1 (78% identical), guinea pig GSTM1 (78% identical), mouse Gstm6 (78% identical), mouse Gstm3 (76% identical), tropical clawed frog gstp1 (32% identical), Caenorhabditis elegans gst-35 (26% identical), zebrafish gstp1.1 (25% identical), Caenorhabditis elegans gst-16 (25% identical), and 37 more. Paralogues in human: GSTM5 (88% identical), GSTM4 (87% identical), GSTM2 (84% identical), GSTM3 (73% identical), GSTP1 (28% identical), GSTA2 (26% identical), GSTA1 (25% identical), GSTA3 (25% identical), GSTA5 (24% identical), HPGDS (24% identical), GSTA4 (23% identical).
Diseases named in the same sentence as GSTM1 in open-access papers:
GSTM1 is named in the same sentence as 306 diseases in open-access papers, as found by Europe PMC text mining. Sharing a sentence is not in itself a finding about the gene and the disease. The quoted sentences say what the papers report.
lung carcinoma (76 papers, 2002 to 2025). "Our finding is compatible with the results reported by several studies that found a significantly increased lung cancer risk by GSTM1 null genotype in different populations." (PMID 39619061, 2024). "In the present study, there was a significant difference in the genotypic frequency of GSTM1 null between lung cancer patients and control and associated with a 1.6-fold increased risk of lung cancer." (PMID 39619061, 2024). "The GSTM1 null genotype was found to be significantly associated with a 1.6-fold increased risk of lung cancer (OR = 1.60, 95%CI = 1.01–2.52, p = 0.049)." (PMID 39619061, 2024). "A homozygous GSTM1-null genotype has been associated with lung cancer pathogenesis, emphysema, and COPD susceptibility." (PMID 36698131, 2023). "The Glutathione S Transferase mu 1 (GSTM1) gene has been linked with lung cancer risk, as it plays a role in toxicity and detoxification." (PMID 37143928, 2023). "The null genotype of the deletion polymorphisms of glutathione-S-transferase theta 1 (GSTT1) and glutathione-S-transferase mu 1 (GSTM1) is frequently associated with lung cancer with evidence of effect modification by tobacco smoking." (PMID 34272429, 2021). "Glutathione S transferase mu 1 (GSTM1) gene has been shown to be associated with lung cancer risk, and the GSTM1 enzyme plays a vital role in the detoxification pathway and protection against toxic insults." (PMID 32030321, 2020). "In a review of glutathione S-transferase M1 (GSTM1) polymorphisms and lung cancer, the median prevalence of the homozygous null genotype was 50% among control subjects in 98 epidemiologic studies." (PMID 30617991, 2019). "Glutathione S transferase mu 1 (GSTM1) gene has been associated with lung cancer (LC) risk, for GSTM1 enzyme playing a vital role in detoxification pathway and protective against toxic insults." (PMID 30123431, 2018). "Decreased copy numbers or null genotype of GSTM1 have been associated with hepatotoxicity and higher risk of many cancers including lung cancer, gastric cancer, and bladder cancer." (PMID 29048532, 2017). "GSTM1 encodes the glutathione-S-transferase (GST) M1 enzyme that is involved in detoxification of various carcinogens in lung cancer." (PMID 29137244, 2017). "When subgroup analysis was performed by source of control, we observed an association between GSTM1 deletion polymorphism and increased lung cancer risk in both healthy subjects-based control and hospitalized patients-based control." (PMID 25797617, 2015). "There were a total of 53 studies with 7,833 cases and 10,353 controls concerning the GSTM1 deletion polymorphism related to lung cancer risk." (PMID 25797617, 2015). "In this paper, we performed a systematic literature review to comprehensively evaluate the association of GSTM1 deletion polymorphism with lung cancer risk in Chinese population." (PMID 25797617, 2015). "Considering that cigarette smoking is an evident risk factor for lung cancer, and that GSTM1 is involved in the metabolism of various carcinogens present in cigarette smoking, a subgroup analysis regarding smoking status was conducted." (PMID 25797617, 2015). "Previous studies have reported the association of glutathione S-transferase M1 (GSTM1) deletion polymorphism with genetic susceptibility of lung cancer in Chinese population." (PMID 25797617, 2015). "We also observed an increased risk of GSTM1 null genotype for lung cancer in stratified analyses by source of control, smoking status and histological type." (PMID 25797617, 2015). "We also observed an increased risk of GSTM1 null genotype for lung cancer stratified by smoking status (OR = 1.60, 95%CI: 1.41–1.81 for smokers and OR = 1.79, 95%CI: 1.54–2.08 for nonsmokers, respectively)." (PMID 25797617, 2015). "The aim of this study was to clarify the association of GSTM1 deletion polymorphism with lung cancer risk in Chinese population." (PMID 25797617, 2015).
lung carcinoma (continued). "We observed an association between GSTM1 null genotype and increased lung cancer risk in stratified analysis by histological type (OR = 1.50, 95%CI: 1.31–1.72 for squamous cell carcinoma and OR = 1.36, 95%CI: 1.08–1.70 for adenocarcinoma, respectively)." (PMID 25797617, 2015). "Genetic mutation of glutathione S-transferase μ1 (GSTM1), a protective enzyme against tissue damage-inducing substances found in tobacco, was more prevalent in lung cancer patients with COPD than in healthy patients." (PMID 26555338, 2015). "We observed an association of GSTM1 deletion polymorphism with increased lung cancer risk in the total population (OR = 1.46, 95%CI: 1.32–1.61 for null vs. present)." (PMID 25797617, 2015). "The results showed a significant association between the GSTM1 null genotype and lung cancer risk in the Chinese population under the random-effects model (OR = 1.20, 95% CI: 1.16 to 1.25, I2 = 45.1%, P<0.001)." (PMID 25036724, 2014). "Most molecular epidemiologic studies suggested an association between GST genetic polymorphisms and lung cancer risk, especially when deletion of GSTM1 is observed in the Asian population." (PMID 25036724, 2014). "Our cumulative meta-analysis demonstrated a stable and reliable result of the relationship between GSTM1 null genotype and lung cancer risk." (PMID 25036724, 2014). "An increased risk of lung cancer with GSTM1 and GSTT1 null genotype, especially with dual null genotype, was found in the Chinese population." (PMID 25036724, 2014). "After omitting these records, the adjusted association of GSTM1 null genetype and lung cancer risk showed a lower heterogeneity and an increased susceptibility (fixed-effects model: OR = 1.23, 95% CI: 1.19 to 1.27, P<0.001)." (PMID 25036724, 2014). "We also identified that smoking further increases the cancer risk, interestingly not only to lung cancers, in people with either GSTM1 or GSTT1 null genotypes." (PMID 24250808, 2013). "A large meta-analysis conducted in 2006, including 19,729 cases and 25,931 controls from 117 studies, found an increased lung cancer risk associated with the GSTM1 present/null polymorphism." (PMID 23013535, 2012). "The association of GSTM1 null polymorphism with different cancers, such as lung cancer, gastric cancer, and bladder cancer, has been extensively explored." (PMID 23071687, 2012). "In this present study, we propose to research the combined effects of CYP1A1 gene and GSTM1 gene polymorphism and their risks to lung cancer." (PMID 21859547, 2011). "Cytochrome P450A1 (CYP1A1) gene and glutathione S-transferase M1 (GSTM1) gene both have single nucleotide polymorphisms and effects on lung cancer." (PMID 21859547, 2011). "We discovered through our meta-analysis that the combined effects of CYP1A1 gene and GSTM1 gene polymorphism are significantly associated with an increased risk to lung cancer." (PMID 21859547, 2011). "The CYP1A1 IIe/Val genotype which carries a homozygous mutant type has a higher chance of risk to lung cancer than that which carries a homozygous mutant type and a heterozygous type when the GSTM1 carries a null genotype." (PMID 21859547, 2011). "Based on McBride's findings, 33% of the participants in the GT arm had a positive genetic test for the missing gene GSTM1 for elevated susceptibility to lung cancer." (PMID 20843376, 2010). "Two hundred and sixty-fve histological confrmed lung cancer patients and 307 health controls were recruited in this case-control study and the relationship between GSTM1 genetic polymorphism and lung cancer risk was investigated." (PMID 20677650, 2010). "Many studies have reported that polymorphism in CYP1A1 as well as in GSTM1, or combination effect of both, have been associated with different types of cancer risk including human lung cancer." (PMID 20704749, 2010).
lung carcinoma (continued). "That is, the smoking-gene interaction means that some smokers are at greater risk of developing lung cancer, with several host characteristics (i.e., K-ras, GSTM1, CYP2D6, c-MET, NKX2-1, LKB1, BRAF) implicated in lung cancer onset." (PMID 20843376, 2010). "The aim of this study is to investigate the relationship between GSTM1 genetic polymorphism and lung cancer risk among Han nationality population in Tianjin district." (PMID 20677650, 2010). "A recent pooled analysis also suggested that genetic polymorphisms in CYP1A1 and GSTM1 are associated with lung cancer risk among Asian populations." (PMID 20704749, 2010). "An early study from Japan reported the combined effects of CYP1A1 MspI genotype and deficient GSTM1 in lung cancer (OR = 16.00), but only at a low-dose level of cigarette smoking." (PMID 20704749, 2010). "A significant association of GSTM1 null genotype with lung cancer has already been observed in two large studies belongs to Japanese and two in Chinese." (PMID 17897446, 2007). "We have investigated GSTM1 gene polymorphisms in healthy subjects and lung cancer patients in the Turkish population and reviewed the control subjects of the studies performed in the Turkish population." (PMID 17897446, 2007). "A meta-analysis of 11 studies found an OR of 1.6 (95% CI = 1.26–2.04) for an association between the GSTM1-null genotype and lung cancer risk." (PMID 17897446, 2007). "Individuals with GSTM1 null genotype also have an increased cancer risk for skin type I and basal cell carcinoma and for smoking and lung cancer." (PMID 18053222, 2007). "Among 180 lung cancer patients, 31.67% carried GSTM1 null allele, and 68.33% were GSTM1 positive." (PMID 39619061, 2024). "The literature includes several studies that have shown that null polymorphisms in GSTM1 could increase the risk of cancer of the head and neck, as well as oral cancer, breast cancer, and lung cancer." (PMID 32882964, 2020). "We hypothesized in present case control study that deletion polymorphism of GSTT1 and GSTM1 higher in lung cancer patients compared to controls as well as with relation to smoking." (PMID 31554367, 2019). "We found increased GSTM1 deletion polymorphism in lung cancer cases (53.34%) than controls (46%)." (PMID 31554367, 2019). "Further, a combination of GSTM1 null genotype with CYP1A1 polymorphisms augmented lung cancer risk." (PMID 27090234, 2016). "Moreover, the GSTM1/GSTT1 null genotype has been reported to confer a slight increase in risk [OR: 1.33 (95% CI: 1.10–1.61)] of lung cancer in a small-scale meta-analysis." (PMID 27045371, 2016). "The association between CYP1A1 and GSTM1 polymorphisms in lung cancer was reported." (PMID 27090234, 2016). "In summary, we observed an increased lung cancer risk in subjects with GSTM1 null genotype." (PMID 25797617, 2015). "The present meta-analysis of 53 published studies including 7,833 cases and 10,353 controls might present a precise estimation of the association of GSTM1 deletion polymorphism with lung cancer risk in Chinese population, owing to including the updated data." (PMID 25797617, 2015). "The findings suggest that GSTM1 deletion polymorphism may contribute to lung cancer risk in Chinese population." (PMID 25797617, 2015). "In subgroup analysis for source of control, we observed an increased risk of lung cancer with GSTM1 null genotype in healthy subjects-based control (OR = 1.48, 95%CI: 1.32–1.66) and hospitalized patients-based control (OR = 1.40, 95%CI: 1.22–1.60), respectively." (PMID 25797617, 2015). "Overall, we observed an association of GSTM1 deletion polymorphism with increased lung cancer risk in Chinese population (odds ratio (OR) = 1.46, 95% confidence interval (95%CI): 1.32–1.66 for null genotype vs. present genotype) based on 53 studies including 7,833 cases and 10,353 controls." (PMID 25797617, 2015).
lung carcinoma (continued). "In conclusion, this comprehensive review demonstrates that GSTM1 null genotype might be a risk factor for lung cancer in the Chinese population." (PMID 25797617, 2015). "Subgroup analysis of the association between GSTM1 null genotype and lung cancer risk." (PMID 25036724, 2014). "Previous meta-analyses suggest that GSTM1 null genotypes might have a correlation with increased susceptibilities to breast cancer and lung cancer in Chinese people." (PMID 22900055, 2012). "High risk for smoking related lung cancer has been reported in individuals deficient in GSTM1." (PMID 22206016, 2011). "Also, another analysis indicated a possible interaction between the CYP1A1*2A allele and GSTM1 deletion on lung cancer risk in Caucasians." (PMID 20704749, 2010). "In addition, a possible association was found between null GSTM1 and NSCLC with promoter hypermethylation of the DAPK or RARβ gene, implying effect of GSTM1 polymorphism on the aberrant methylations of TSG in lung cancer." (PMID 20704749, 2010). "Many studies showed that GSTM1 genetic polymorphism was associated with lung cancer risk." (PMID 20677650, 2010). "Previous meta-analyses indicate that GSTM1 deficiency might have a significant association with increased risks of breast cancer and lung cancer in Chinese people." (PMID 19338664, 2009). "Finally, mutation and dysfunction of the detoxifier GSTM1 is related to high risk of head and neck and lung cancer in smokers." (PMID 19662092, 2009). "Study on relation between GSTM1 and lung cancer on smokers showed that the risk of lung cancer is higher among smokers with GSTM1 null genotype and not receiving α-tocopherol supplementation compare with those on smokers with GSTM1 null genotype and receiving α-tocopherol supplementation." (PMID 36793931, 2023). "Previous studies have reported a high correlation between GSTM1 and lung carcinogenesis, with evidence suggesting that individuals with common GSTM1 polymorphisms, including other Glutathione S-transferase genes, could be more susceptible to lung cancer upon exposure to tobacco." (PMID 37143928, 2023). "Therefore, patients carrying the mutant version of GSTM1 show the highest risk of lung cancer." (PMID 34235071, 2021). "In order to obtain a more precise estimation of this relationship, a meta-analysis including a total of 53 studies was conducted, which may provide more comprehensive evidence for the association of GSTM1 deletion polymorphism with lung cancer risk in Chinese population." (PMID 25797617, 2015). "Accordingly, this study is aimed at investigating GSTM1 and GSTT1 polymorphisms' association with lung cancer risk and their effects on the toxicities of platinum-based chemotherapy used to treat Bangladeshi lung cancer patients." (PMID 39619061, 2024). "This population-based case–control study with 180 lung cancer patients and 200 healthy controls chose to investigate the links between GST (GSTM1 and GSTT1) polymorphisms and lung cancer susceptibility in the Bangladeshi population." (PMID 39619061, 2024). "Amidst the diverse array of xenobiotic-metabolizing enzymes, the implication of GSTM1 and GSTT1 in modulating lung cancer risk stems from their potential roles in carcinogen metabolism." (PMID 39619061, 2024). "There was a significant difference in GSTM1 null genotype frequency distribution between lung cancer patients and controls." (PMID 39619061, 2024). "Several studies have proclaimed that the GSTM1 expression is closely related to the poorer prognosis of colorectal cancer, breast cancer, and lung cancer." (PMID 36263204, 2022). "In general, these data suggested that the notable GSH high‐consumption state in lung cancer BM was caused by the upregulation of GPX4 and GSTM1." (PMID 34586745, 2021). "Previous studies have shown that polymorphisms in CYP1A1 and GSTM1 and EGFR contribute to the increased risk of females for lung cancer." (PMID 32344833, 2020).